METTL16 (methyltransferase 16, RNA N6-adenosine)
Diseases named in the same sentence as METTL16 in open-access papers (continued):
Sharing a sentence is not in itself a finding about the gene and the disease.
melanoma (2 papers, 2021 to 2023). A malignant, usually aggressive tumor composed of atypical, neoplastic melanocytes. "A three-gene prognostic signature including IGF2BP3, RBM15B, and METTL16 was constructed, and the risk score of this signature was identified to be an independent prognostic indicator for melanoma." (PMID 34446007, 2021). "Coefficients obtained from multivariate Cox analysis were conducted to calculate each melanoma patient’s risk score utilizing the following formula: risk score = (0.675902669) × RBM15B + (0.6078590311) × METTL16 + (0.555973734) × IGF2BP3." (PMID 34446007, 2021). "Besides, RBM15B and METTL16 in the signature may influence melanoma tumor promotion because they were associated with poor OS in the TCGA database." (PMID 34446007, 2021). "The results demonstrated that IGF2BP3 mRNA level was upregulated in melanoma tissues as well, while RBM15B and METTL16 was insignificant, though high expression of RBM15B and METTL16 were associated with poor OS in TCGA database." (PMID 34446007, 2021). "Thirdly, we also preliminary explored novel potential carcinogenic mechanisms of IGF2BP3 with GSEA as well as the role of RBM15B and METTL16 in melanoma, making our study more innovative and colorful." (PMID 34446007, 2021). "Next, based on variables of three hub genes (IGF2BP3, METTL16, and RBM15B) expression derived from the all TCGA cohort, a nomogram was constructed to predict the 1-, 2-, and 3-year survival probabilities of melanoma patients." (PMID 34446007, 2021). "Third, the three prognostic panel genes (IGF2BP3, METTL16, and RBM15B) not only influenced the prognosis and clinicopathological features but were also closely correlated with tumorigenesis key signaling pathways, and hallmarks of malignant melanoma." (PMID 34446007, 2021).
non-alcoholic fatty liver disease (2 papers, 2022 to 2023). "For example, METTL16 mediated the translation of CIDEA in a m6A-dependent manner and promoted non-alcoholic fatty liver disease." (PMID 37647025, 2023).
prostate tumors (2 papers, 2021 to 2026). "Seven regulators, including IGF2BP2, METTL3, METTL16, ZNF217, ZC3H13, RBM15B, and PRRC2A, exhibited significant correlations between CNVs and gene expression levels in prostate tumors." (PMID 34899855, 2021).
rectal cancer (2 papers, 2021 to 2022). A primary or metastatic malignant neoplasm that affects the rectum. "Bioinformatics analysis found that METTL16 is expressed in large amounts in colon cancer, but not in rectal cancer." (PMID 35047058, 2022).
Sepsis (2 papers, 2023 to 2024). Sepsis is defined as life-threatening organ dysfunction caused by a dysregulated host response to infection. "Based on RF, this study screened the characteristic gene METTL16 as the most important gene in advanced sepsis." (PMID 37330481, 2023). "Clinical studies have identified genes such as WTAP and methyltransferase-like protein 16 (METTL16), which, through the modulation of m6A methylation, facilitate immune cell infiltration, accelerating the onset and progression of sepsis in both healthy individuals and late-stage sepsis patients." (PMID 39234245, 2024). "Our study found that METTL16 gene was significantly positively correlated with the proportion of multiple immune cells, suggesting that METTL16 may promote the infiltration of immune cells in the occurrence and development of sepsis." (PMID 37330481, 2023).
thyroid cancer (2 papers, 2025). "METTL16, an m6A writer, was found to be highly expressed in thyroid cancer and to promote the proliferation, migration, and invasion of thyroid cancer." (PMID 40819127, 2025). "The same study identified SAMD11 as a target gene of METTL16, with METTL16 regulating SAMD11 expression through m6A modification, thus playing a crucial role in thyroid cancer." (PMID 40819127, 2025).
amyotrophic lateral sclerosis (1 paper, 2025). Amyotrophic lateral sclerosis (ALS) is a neurodegenerative disease characterized by progressive muscular paralysis reflecting degeneration of motor neurons in the primary motor cortex, corticospinal tracts, brainstem and spinal cord. "The enrichment of KEGG related to METTL16 is the amyotrophic lateral sclerosis signaling and RNA transport pathway." (PMID 40015977, 2025).
anemia (1 paper, 2022). A reduction in the number of red blood cells, the amount of hemoglobin, and/or the volume of packed red blood cells. "In CD71+Ter119– stage, the change in transcriptome under Mettl16 deficiency was modest, and most of the differentially regulated genes were associated with the hypoxic response, which was attributable to severe anemia in Mettl16fl/flEpor-Cre+ mice." (PMID 36307435, 2022).
COVID-19 (1 paper, 2022). A disease caused by infection with severe acute respiratory syndrome coronavirus 2. "COVID-19 patients with high expression levels of FTO tend to display high levels of METTL3, METTL16, RBM15B, or VIRMA." (PMID 35655464, 2022).
disc degeneration (1 paper, 2022). "To investigate the function of MAT2A and METTL16 in the apoptosis of NPCs and finally their role in the pathogenesis of disc degeneration, we downregulated the expression of MAT2A in NPCs with small interfering RNA (siRNA) while upregulated the expression of METTL16 in the NPCs with lentivirus." (PMID 35069973, 2022).
glioblastoma (1 paper, 2026). The most malignant astrocytic tumor (WHO grade IV). "Furthermore, METTL16 expression is associated with clinical characteristics in glioblastoma, such as isocitrate dehydrogenase status, molecular subtype, and treatment response." (PMID 41459114, 2026).
Intellectual disability (1 paper, 2025). "METTL16 had the highest overall number of intellectual disability co-regulated proteins with 55 and was the only effector protein which had NSUN2 listed as an ID co-regulated protein." (PMID 39499421, 2025).
intervertebral disc degeneration (1 paper, 2023). "Degradation of MAT2A pre-mRNA mediated by METTL16 was disrupted by oxidative stress, which consequently aggravated the apoptosis of nucleus pulposus cells and exacerbated the process of intervertebral disc degeneration." (PMID 37647025, 2023).
intestinal cancer (1 paper, 2025). "METTL16 G110C, which was identified in intestinal cancer, did not significantly alter binding to U6 snRNA; however, the KD2 value for SAM binding was greater than 1000 μM and the observed rate constant at 1 mM SAM was barely measurable: 0.005 ± 0.003 min−1." (PMID 41007290, 2025).
ischemia (1 paper, 2023). A hypoperfusion of the BLOOD through an organ or tissue caused by a PATHOLOGIC CONSTRICTION or obstruction of its BLOOD VESSELS, or an absence of BLOOD CIRCULATION. "In addition, qRT-PCR and Western blotting also confirmed that the expression of METTL16 and LRPPRC was downregulated and the expression of RBM15 was upregulated after ischemia." (PMID 37139237, 2023).
memory impairment (1 paper, 2022). "Artificial knockdown of METTL16 in the hippocampi has been found to result in synaptic disorders and memory impairments by inhibiting the stability of MAT2A mRNA." (PMID 36307396, 2022).
metastatic tumors (1 paper, 2024). "Furthermore, the expression levels of METTL16 were lower in stage III/IV and metastatic tumors compared to stage I/II and nonmetastatic tumors." (PMID 38334797, 2024).
osteoporosis (1 paper, 2025). A condition of reduced bone mass, with decreased cortical thickness and a decrease in the number and size of the trabeculae of cancellous bone (but normal chemical composition), resulting in increased fracture incidence. "The in vivo animal experiments confirmed the pivotal role of the METTL16-PPARγ axis in osteoporosis development in mice." (PMID 40210616, 2025). "This study utilized advanced single-cell RNA sequencing (scRNA-seq) and Bulk RNA-seq techniques to explore how METTL16 influences the osteogenic differentiation of Bone Marrow-Derived Mesenchymal Stem Cells (BMSCs) and its implication in osteoporosis." (PMID 40210616, 2025).
pulpitis (1 paper, 2023). Inflammation of the dental pulp. "The results showed that there were significant differences in the genes ALKBH5, METTL14, METTL3, METTL16, RBM15B and YTHDF1 between normal group and the pulpitis group." (PMID 37978362, 2023). "However, YTHDF1, YTHDF3, METTL16 and METTL3 gene expression were not statistically different between the pulpitis group and the control group, and RBM15B, ZCCHC4 and ALKBH5 were up-regulated." (PMID 37978362, 2023).
respiratory allergies (1 paper, 2023). "Another example is Th2 cells, whose hyperactivation is key to respiratory allergy, whereas the number of Th2 cells was negatively correlated with METTL16 expression and positively correlated with RBM15B expression in our results." (PMID 37328853, 2023). "However, the molecular mechanism by which METTL16 regulates macrophages in respiratory allergies requires further in-depth study." (PMID 37328853, 2023). "Therefore, we hypothesized that the expression of METTL14, METTL16, and RBM15B closely influences the pathogenesis of respiratory allergies in mast and Th2 cells." (PMID 37328853, 2023).
thalassemia (1 paper, 2024). An inherited blood disorder characterized by a decreased synthesis of one of the polypeptide chains that form hemoglobin. "Then, we performed qRT-PCR and found that the relative expression of METTL16 and YTHDF3 mRNAs in patients with HbH and HbH-CS diseases was lower than that in normal controls without thalassemia." (PMID 39088431, 2024).
tumor (66 papers, 2020 to 2026). "Large-scale data analysis revealed that the expression of m6A regulators, including METTL16, is closely associated with immune cell infiltration in the tumor microenvironment." (PMID 41459114, 2026). "In this review, we provide a narrative review of the functions of METTL16 and summarize its oncogenic and tumor-suppressive functions as well as its underlying mechanisms in human digestive system cancers." (PMID 41695366, 2026). "Gene editing tools like CRISPR/Cas9 can be employed to directly regulate the expression or function of METTL16, repair its mutations in tumor cells, and restore normal DNA damage repair capabilities." (PMID 41459114, 2026). "The METTL16 abundance has been found increased in cholangiocarcinoma tissues and its deficiency inhibits cell proliferation and tumor progression by reducing YTHDF1-mediated translation process of target mRNA PRDM15." (PMID 40734692, 2025). "The novel m6A methyltransferase METTL16 has been implicated in modulating key gene expression and signaling pathways, thereby influencing tumor proliferation, invasion, and chemotherapy response." (PMID 41322419, 2025). "A recent study reports that METTL16 was upregulated in GC, exerting a crucial role in the growth of tumor in vivo, which are associated with cyclin D1 expression by blocking G1/S phase." (PMID 39009956, 2024). "Using CCK8 assay and colony formation assay, we observed that 25μM CQ inhibited the tumor cell proliferation caused by METTL16 knockdown." (PMID 38385084, 2024). "Collectively, these findings highlight the prognostic value of METTL16 and its potential underlying mechanism in the tumor microenvironment in PDA." (PMID 36158188, 2022). "Additionally, elucidating the precise molecular mechanisms underlying METTL16-mediated oncogenesis and tumor progression is essential for the rational design of targeted therapies." (PMID 41459114, 2026). "The regulation of the METTL16 pattern participates in multiple biological processes and may leads to tumor initiation or progression when it affects tumor associated genes." (PMID 40015977, 2025). "In addition to modulating immune checkpoints, Mettl16 influences the polarization of tumor-associated macrophages (TAMs), a key component of the immune infiltrate in solid tumors." (PMID 39911396, 2025). "Recent studies have highlighted the critical role of RNA m6A modification in PAAD development, with the novel m6A methyltransferase METTL16 implicated in regulating key gene expression and signaling pathways, thereby influencing tumor proliferation, invasion, and therapeutic response." (PMID 41322419, 2025). "However, current studies only explored that METTL16 was linked to a few cancer types, and its biological role remains unexplored in most tumor types." (PMID 40015977, 2025). "Specifically, METTL16-mediated RNA modifications could influence the function and distribution of tumor-associated immune cells, such as tumor-infiltrating lymphocytes and macrophages, thereby contributing to immune evasion and therapy resistance." (PMID 41322419, 2025). "Furthermore, METTL16 has been implicated in a large number of cancer studies with both oncogenic and tumor-suppressive effects associated with changes in METTL16 expression levels." (PMID 37504262, 2023). "The results revealed that IGF2BP3, RBM15B, and METTL16 mutations may be potential biomarkers for certain anti-tumor therapies." (PMID 34446007, 2021). "Conducting a detailed comparison of METTL16 with the canonical METTL3–METTL14 complex is critically important for uncovering the distinctive functions that METTL16 exerts in tumor initiation and progression." (PMID 41459114, 2026). "Aberrant phosphorylation of METTL16 can disrupt RNA methylation patterns in cancer cells, influencing tumor growth and metastasis." (PMID 41459114, 2026).
tumor (continued). "These transcriptional regulatory mechanisms are crucial for the functional state of cells and tumor progression, particularly in the context of METTL16's role in cancer development." (PMID 41459114, 2026). "METTL16 exerts profound effects on core processes in tumor cells by regulating a multilayered RNA network, including U6 snRNA, ncRNA, lncRNA, and rRNA." (PMID 41459114, 2026). "METTL16 also modulates immune-related processes within the tumor microenvironment, influencing tumor immune evasion, inflammation, and anti-tumor immunity." (PMID 41459114, 2026). "This dual functionality is influenced by tumor type, genetic background, and interactions with other molecular pathways, underscoring the complexity of METTL16 in cancer progression." (PMID 41459114, 2026). "METTL16 expression is also closely related to tumor staging, grading, and metastatic status, providing valuable insights into its prognostic potential for specific cancer types." (PMID 41459114, 2026). "The METTL16 knockdown groups demonstrated reduced tumor size and slower tumor growth in vivo experiments compared to the control group." (PMID 40095756, 2025). "Next, we evaluated the differential expression of METTL16 in patients with different tumor types in terms of clinical information by TIMER2 tools." (PMID 40015977, 2025). "Mechanistically, METTL16 regulates mRNA stability and translation via recognition of m6A sites on oncogenes or tumor suppressors, and its expression is modulated by upstream factors such as transcription factors and hypoxia-inducible signals." (PMID 41322419, 2025). "METTL16 promotes GC cell proliferation and tumor growth in vivo, whereas its downregulation inhibits proliferation by arresting the G1/S cell cycle transition." (PMID 41322419, 2025). "METTL16 exerts diverse functions across different tumor types by modulating cancer cell proliferation, migration, invasion, as well as the TME and immune responses." (PMID 41322419, 2025). "Current research indicates that METTL16 plays a dual role in cancer biology, either promoting or inhibiting tumor progression depending on the context." (PMID 41256854, 2025). "In vivo, METTL16 overexpression induces tumor growth, increases LAMA4 and COL4A1 expression, and enhances cisplatin resistance." (PMID 41322419, 2025). "Methyltransferase-like 16 (METTL16), a recently identified m6A methyltransferase, has been shown to influence tumor progression through m6A-dependent regulation of key target genes." (PMID 41322419, 2025). "Inhibition of Mettl16 has been shown to downregulate PD-L1 expression, enhancing T cell-mediated anti-tumor responses and improving the efficacy of immunotherapies such as PD-1/PD-L1 blockade." (PMID 39911396, 2025). "In xenograft mouse models, NCTD administration significantly reduces tumor volume and downregulates METTL16, MAT2A, PP2A, and vascular endothelial growth factor (VEGF) expression." (PMID 41322419, 2025). "Inhibition of METTL16’s methyltransferase activity can affect tumor cell RNA stability, splicing, and translation, thereby suppressing proliferation and invasion." (PMID 41322419, 2025). "By modulating the expression of cytokines and chemokines involved in Treg recruitment and activation, Mettl16 contributes to their accumulation in the tumor microenvironment, further exacerbating immune suppression." (PMID 39911396, 2025). "Although METTL16 has emerged as an important m6A methyltransferase with diverse roles in RNA processing and cellular homeostasis, its involvement in tumor immunity remains poorly explored." (PMID 41322419, 2025). "Functional studies demonstrate that METTL16 exerts tumor-suppressive effects: upregulation inhibits tumor cell growth and invasion, while downregulation promotes tumor progression." (PMID 41322419, 2025). "Collectively, METTL16 emerges as a pivotal epitranscriptomic regulator linking RNA modification, tumor progression, and immune modulation, offering new avenues for precision oncology." (PMID 41322419, 2025).